ENSG00000300811 (novel transcript, antisense to SYNE1)
Gene: Long non-coding RNA gene on chromosome 6 (152,129,840 to 152,162,937, forward strand). Ensembl gene ENSG00000300811.
Gene Ontology:
Biological process: SRP-dependent cotranslational protein targeting to membrane, signal sequence recognition
Cellular component: signal recognition particle, endoplasmic reticulum targeting